PER2 (period circadian regulator 2)
Diseases named in the same sentence as PER2 in open-access papers (continued):
Sharing a sentence is not in itself a finding about the gene and the disease.
epilepsy (3 papers, 2020 to 2025). A brain disorder characterized by episodes of abnormally increased neuronal discharge resulting in transient episodes of sensory or motor neurological dysfunction, or psychic dysfunction. "This is exemplified by genes such as KCND2, whose mutation contributes to epilepsy and whose own expression is commanded by the core clock gene PER2." (PMID 40940742, 2025). "In the rat pilocarpine model, epileptic and naïve rats were compared at specific ZT points following the development of spontaneous seizures, with results showing that development of epilepsy is associated with alterations in rhythmic changes of all three period genes (Per1, Per2, and Per3)." (PMID 32714261, 2020). "The PER gene family (PER1, PER2, and PER3) exhibits complex alterations in epilepsy models." (PMID 40940742, 2025). "Interestingly, the circadian clock pathway was enriched in GO analysis, and several circadian clock genes, such as PER2 and PER3, were regarded as epilepsy-related genes, indicative of circadian involvement in epilepsies/seizures." (PMID 36835631, 2023). "Mutations in PER2 and CRY1 result in advanced phase sleep disorder and delayed phase sleep disorder, respectively; however, neither of these phenotypes includes epilepsy." (PMID 32714261, 2020).
liver fibrosis (3 papers, 2017 to 2022). "Diminution of the expression of Per2 exacerbates liver fibrosis and vascular senescence." (PMID 29186898, 2017). "Per2 expression plays a protective role in hepatic fibrosis." (PMID 29186898, 2017).
non-Hodgkin lymphoma (3 papers, 2017 to 2018). Distinct from Hodgkin lymphoma both morphologically and biologically, non-Hodgkin lymphoma (NHL) is characterized by the absence of Reed-Sternberg cells, can occur at any age, and usually presents as a localized or generalized lymphadenopathy associated with fever and weight loss. "Disrupted CRY2 and PER2 are associated with non-Hodgkin’s lymphoma and the initiation and/or progression of AML, respectively, and CpG islands of PER3 are highly methylated in all patients with chronic myelogenous leukemia." (PMID 28487473, 2017).
pituitary adenoma (3 papers, 2023 to 2024). "Conversely, loss of Per2 protects mice against developing estrogen-induced pituitary adenoma." (PMID 37215573, 2023). "Altogether, inhibition of PER2 by SR8278 protected mice from developing pituitary adenoma probably through limiting cell cycle progression." (PMID 37215573, 2023). "RNA-seq analysis suggests involvement of cell cycle disturbance in PER2 regulation of pituitary adenoma." (PMID 37215573, 2023). "Thus, we have established PER2 as an integrator of circadian clock with pituitary adenomas, providing new insights to the molecular mechanisms behind clock-controlled tumorigenesis." (PMID 37215573, 2023). "Our study suggests the core clock component PER2 as a novel common drug target for management of GHPA and PRLPA because PER2 acts as a pro-oncogenic protein for these two types of pituitary adenomas and the small molecule SR8278 decreases PER2 expression and mitigates tumor growth." (PMID 37215573, 2023). "Estrogen-induced pituitary adenoma could be inhibited by SR8278 through reducing the expression of PER2." (PMID 37950289, 2023). "In fact, pituitary adenoma cell proliferation displays a robust 24-h rhythm with a higher rate of proliferation during the dark period, consistent with the diurnal profile of PER2 as a positive cell cycle regulator." (PMID 37215573, 2023). "In pituitary adenomas, the rhythmicity of PER2 retained but with a decreased amplitude." (PMID 37215573, 2023). "Because among core clock genes, PER2 was prominently disrupted in the pituitary adenomas and Per2 disruption is related to jetlag-induced GH3 tumor growth, we next investigated whether PER2 indeed affects pituitary tumorigenesis." (PMID 37215573, 2023). "PER2 promotes pituitary tumourigenesis, and downregulation of PER2 by SR8278, a circadian nuclear receptor REV-ERBα antagonist, protected mice from developing pituitary adenoma." (PMID 39413708, 2024). "It is noteworthy that the tumor-promoting effects of PER2 may be not limited to GHPA and PRLPA only because elevations in PER2 protein were similarly observed in other subtypes of pituitary adenomas such as TSH- and ATCH-secreting types." (PMID 37215573, 2023). "Likewise, pituitary PER2 was up-regulated in a mouse model of PRLPA induced by estrogen, and in pituitary adenoma GH3 and MMQ cells." (PMID 37215573, 2023).
psoriasis (3 papers, 2021 to 2023). An autoimmune condition characterized by red, well-delineated plaques with silvery scales that are usually on the extensor surfaces and scalp. "In another mouse model where psoriasis was induced via TLR7, CLOCK and Per2 were found to regulate the severity of psoriasis via the direct modulation of the expression of IL23R." (PMID 36982706, 2023).
Arrhythmia (2 papers, 2017 to 2022). Any cardiac rhythm other than the normal sinus rhythm. "It has previously been shown that constitutive expression of Per2 causes arrhythmia in vitro and in vivo." (PMID 29227248, 2017). "In our study, we observed serious arrhythmia of 5 × FAD mice, including the altered activity–rest cycle, peripheral Per2 expression, and GLP-1 secretion." (PMID 36148311, 2022).
cervical carcinoma (2 papers, 2021 to 2025). A carcinoma arising from either the exocervical squamous epithelium or the endocervical glandular epithelium. "Rhythms of drug sensitivity were similarly dampened in cervical carcinoma cells (C33A) that carry an inactivating mutation in the retinoblastoma (RB) tumor suppressor and lack cellular oscillations of Per2 promoter–driven luciferase (pPer2-dLuc)." (PMID 33579708, 2021). "Another CRRG, PER2, has been confirmed to be indirectly regulated by methylation and exhibits low expression in cervical cancer." (PMID 39944833, 2025).
chronic kidney disease (2 papers, 2021 to 2023). Impairment of the renal function secondary to chronic kidney damage persisting for three or more months. "Meanwhile, the kidney explants from chronic kidney disease mice expressed altered PER2::LUC rhythms with significantly longer period compared to control mice." (PMID 34207942, 2021). "In addition, the SCN of PER2::LUC mice with adenine-induced chronic kidney disease displayed dampened amplitude rhythms in their central circadian clock as measured by bioluminescence." (PMID 34207942, 2021).
chronic myelogenous leukemia (2 papers, 2015 to 2017). "It has been demonstrated that the expression levels of the human CRY1, CRY2, PER1, PER2, PER3, and BMAL1 genes were down-regulated in both the chronic phase and blast crisis in chronic myeloid leukemia (CML)." (PMID 26253128, 2015).
cutaneous melanoma (2 papers, 2021 to 2023). A primary melanoma arising from atypical melanocytes in the skin. "According to the cBioPortal and TIMER 2.0 database, the most mutated circadian genes among cutaneous melanoma patients were PER1, PER2, RORB and RORC." (PMID 37373286, 2023).
diffuse large B-cell lymphoma (2 papers, 2013 to 2021). "In addition, it has been reported that CEBPA-regulated PER2 activation is a potential tumor suppressor pathway in diffuse large B-cell lymphoma (DLBCL)." (PMID 34178023, 2021).
esophageal squamous cell carcinoma (2 papers, 2019 to 2021). Esophageal squamous cell carcinoma (ESCC) is a type of esophageal carcinoma (EC) that can affect any part of the esophagus, but is usually located in the upper or middle third. "Their result showed that the expression of clock genes PER1 and PER2 were decreased significantly in esophageal squamous cell carcinoma (ESCC) tumors with different proliferation, differentiation and different TNM stage." (PMID 31151182, 2019). "In addition, our results also clearly evidence an oscillation of PER2 expression in esophageal squamous cell carcinoma (eSCC) cells from two different species." (PMID 33810377, 2021).
Hepatic steatosis (2 papers, 2022). Steatosis is a term used to denote lipid accumulation within hepatocytes. "In the present study, we ascertained that the TRF strategy, hepatocyte-specific knockout of Per2, and the application of a ferroptotic inhibitor not only improved metabolic indices and liver enzymes but also reduced liver steatosis, inflammation, and fibrosis induced by HFHFD." (PMID 36285301, 2022).
Impaired glucose tolerance (2 papers, 2022 to 2024). An abnormal resistance to glucose, i.e., a reduction in the ability to maintain glucose levels in the blood stream within normal limits following oral or intravenous administration of glucose. "Both Cry2 and Per2 SNPs have been associated with impaired glucose tolerance, while Per2 SNPs have also been associated with binge eating and stress related to dieting, leading to increased weight gain." (PMID 36034454, 2022). "Cry2 and Per2 SNP carriers have impaired glucose tolerance, while Per2 SNP carriers who overeat and eat stress-relatedly gain weight." (PMID 39062777, 2024).
infarction (2 papers, 2014 to 2024). A localised pathological necrosis of tissue resulting from obstruction of the blood supply usually by a thrombus, an embolus, or vascular torsion. "Therefore, reduced circulating EPCs early after MI by per2 deficiency likely contributed to decreased capillary density in the peri-infarct area, thus leading to impaired cardiac remodeling and function 28 days post-infarction." (PMID 25268972, 2014).
liposarcoma (2 papers, 2018 to 2019). A usually painless malignant tumor that arises from adipose tissue. "rs7602358 located upstream PER2 was significantly associated with liposarcoma survival (HR: 1.98; 95% CI 1.02–3.85; P = 0.04)." (PMID 30518396, 2018). "rs7602358 located upstream PER2 was significantly associated with liposarcoma survival (HR 1.98; 95% CI 1.02–3.85; P = 0.04) employing an additive genetic model." (PMID 30518396, 2018). "Employing an additive model of inheritance CLOCK rs1801260 and PER2 rs934945 were statistically significantly associated with liposarcoma, while NPAS2 rs895520 and RORA rs339972 were statistically significantly associated with leiomyosarcoma." (PMID 30518396, 2018). "In particular, rs7602358 located upstream PER2, was significantly associated with liposarcoma prognosis." (PMID 30518396, 2018). "The present analysis suggested that carriers of the minor allele of the CLOCK polymorphism rs1801260 (C) or of PER2 rs934945 (T) had a reduced predisposition to sarcoma (26% and 35% respectively with the additive model) and liposarcoma (33% and 41% respectively)." (PMID 30518396, 2018). "Since it has been proposed that liposarcoma could arise from the dedifferentiation of fat cells, one could hypothesize a specific role of CLOCK and PER2 genes and this aspect, worth to be investigated, could open the avenue to new therapeutic targets." (PMID 30518396, 2018).
lung adenocarcinoma (2 papers, 2021 to 2024). A carcinoma that arises from the lung and is characterized by the presence of malignant glandular epithelial cells. "Similarly, by multi-omics computation techniques, several core circadian clock genes are found changed epigenetically in lung adenocarcinomas and lung squamous cell carcinomas, which are involved in cell cycle and apoptosis, such as PER2 and RORA." (PMID 33816508, 2021).
neuroblastoma (2 papers, 2011 to 2022). Neuroblastoma (NB) is the most common solid, extracranial childhood tumor. "Along these lines, knocking down Ubr4 expression in murine neuroblastoma (Neuro-2a) cells also reduced the abundance of ectopically expressed V5-tagged PER2." (PMID 35332162, 2022). "To this end we analyzed the expression and subcellular localization of a GFP-tagged version of PER2 in NG108-15 neuroblastoma cells, since this cell line is of neuronal and glial origin." (PMID 21712997, 2011). "In our study, we found only a minor effect of PP1 on the stability of PER2 in the brain and of overexpressed full-length PER2 in NG 108-15 neuroblastoma cells." (PMID 21712997, 2011). "Moreover, a larger fraction of PER2-GFP was located in the nucleus of neuroblastoma cells expressing I-1* or NIPP1* compared to control cells." (PMID 21712997, 2011).
non‐alcoholic steatohepatitis (2 papers, 2020 to 2023). "PER2 plays an important role in liver diurnal metabolism, regulation of lipid metabolism, and glucose homeostasis, and exacerbates nonalcoholic steatohepatitis, a progressive form of NAFLD." (PMID 38250971, 2023).
oral cancer (2 papers, 2020 to 2022). "In oral cancer, the expression of Per2 reportedly has a positive correlation with PTEN." (PMID 32426819, 2020).
osteoporosis (2 papers, 2010 to 2015). A condition of reduced bone mass, with decreased cortical thickness and a decrease in the number and size of the trabeculae of cancellous bone (but normal chemical composition), resulting in increased fracture incidence. "Future research should investigate whether specific pharmaceutical targeting of the Per2 gene can serve as a new therapeutic avenue to treat bone loss conditions such as osteoporosis." (PMID 26580614, 2015). "Future studies will show whether specific pharmaceutical targeting of Cry2 or Per2 can serve as a new therapeutic avenue to treat bone loss conditions such as osteoporosis." (PMID 20634945, 2010).
subarachnoid hemorrhage (2 papers, 2021 to 2023). A serious neurological disorder characterized by intracranial hemorrhage into the subarachnoid space. "While it has been asserted that microglia upregulate HO1 expression in response to subarachnoid hemorrhage and this upregulation can be observed in neuronal tissue as well as human CSF, there have been no studies yet that correlate neuronal tissue Per2 expression with availability in CSF." (PMID 33562664, 2021).
thyroid nodule (2 papers, 2020 to 2022). A small circumscribed mass in the THYROID GLAND that can be of neoplastic growth or non-neoplastic abnormality. "Therefore, close observation of thyroid nodule clock gene expression and oscillation, especially those of PER2, could be a valuable prognostic indicator in thyroid nodules of elderly patients." (PMID 36284088, 2022). "Furthermore, variants of various clock genes (PER2–3, CRYs, BMAL1, REV-ERBs and RORs) and strong changes in their expression profile have been found on thyroid nodule malignant transformation and have been proposed as potential biomarkers for thyroid nodule pre-operative diagnostics." (PMID 33114365, 2020).
triple-negative breast carcinoma (2 papers, 2018 to 2022). An invasive breast carcinoma which is negative for expression of estrogen receptor (ER), progesterone receptor (PR), and human epidermal growth factor receptor 2 (HER2). "For example, mice bearing triple negative breast cancer can impact the hepatic circadian gene expression causing alterations in several genes including the core clock genes Rev-Erba (Nr1d1), PER2, RORγ, and CLOCK26." (PMID 35046467, 2022).
ulcerative colitis (2 papers, 2022 to 2025). An inflammatory bowel disease involving the mucosal surface of the large intestine and rectum. "Further studies of the relationship between circadian disruption and ulcerative colitis severity require larger sample sizes, longer follow-up, and use of a Per2 knockout animal model." (PMID 35720196, 2022). "Given that Per2 can reduce ATP production by reducing Drp1 phosphorylation at ser637 and the level of ATP is closely related to cell proliferation, a poor proliferation of intestinal epithelial cells is the key factor in the delayed recovery of patients with ulcerative colitis." (PMID 35720196, 2022). "PER2 downregulated a disintegrin and metalloproteinase 12 (ADAM12) expression by reducing its binding activity, thereby suppressing IFN‐γ production in CD4 + T cells of ulcerative colitis." (PMID 40911428, 2025).
adenoma (1 paper, 2015). A neoplasm arising from the epithelium. "Data for PER1, PER2 and PER3 expression in adenomas relative to normal tissue were retrieved from the Oncomine microarray database." (PMID 25501848, 2015). "A statistically significant reduction in PER3 expression was observed in adenomas relative to normal tissue among each of the available data sets; similar differences were noted for PER1, and to a lesser extent PER2 expression." (PMID 25501848, 2015).
allergic rhinitis (1 paper, 2018). Inflammation of the nasal mucous membranes caused by an IgE-mediated response to external allergens. "The present study investigates the expression level and distribution pattern of PER1, PER2, CLOCK, and BMAL1 genes in nasal mucosa of healthy controls, allergic rhinitis patients, and normal rats." (PMID 29534090, 2018).
anaemia (1 paper, 2022). "Per1/2‐null hosts tend to experience greater anaemia than WT hosts because mice deficient in Per2 exhibit high susceptibility to acute erythrocyte stressors." (PMID 34778983, 2022).
aneurysm (1 paper, 2021). Bulging or ballooning in an area of an artery secondary to arterial wall weakening. "In this clinical observational study, circadian rhythm gene Period-2 (Per2) mRNA expression levels were determined from blood leukocytes and cerebrospinal fluid (CSF) cells via real-time PCR on days 1, 7 and 14 after aneurysm rupture in 49 patients with spontaneous SAH." (PMID 33562664, 2021).
arteriosclerosis (1 paper, 2017). A vascular disorder characterized by thickening and hardening of the walls of the arteries. "Interestingly, we found that the Per2 mutation promoted adiposity, another risk factor for arteriosclerosis." (PMID 28499924, 2017). "Given the suggestion that Per2 mutation-induced progression of arteriosclerosis was not attributable to the increase in plasma lipid concentrations, we examined the possible contribution of other risk factors of arteriosclerosis progression using mice 20 weeks after the start of exposure to the HFD." (PMID 28499924, 2017). "Given these previous findings, the Per2 mutation-induced increase in plasma IL-6 may be caused not only by adiposity-triggered inflammation but also by decreased REV-ERBα expression in macrophages, leading to modification of arteriosclerosis." (PMID 28499924, 2017).
atherosclerosis (1 paper, 2009). A disease characterized by the build-up of fatty material and calcium deposition in the arterial wall resulting in partial or complete occlusion of the arterial lumen. "For example, the transcription of Per2 is regulated by RXRα, the ligand of PPARα, which regulates lipid and lipoprotein metabolism, and inflammation, major risk factors for atherosclerosis." (PMID 20040117, 2009).
autism spectrum disorder (1 paper, 2025). A spectrum of developmental disorders that includes autism, and Asperger syndrome. "Perhaps unsurprisingly, variants in PER2 have now been identified in people with autism spectrum disorder with variable sleep phenotypes, including sleep timing." (PMID 40720646, 2025).
Azoospermia (1 paper, 2022). Absence of any measurable level of sperm,whereby spermatozoa cannot be observed even after centrifugation of the semen pellet. "Further bioinformatics mining revealed that related clock genes (PER1, PER2, CRY2, NR1D1 and NPAS2) were down-regulated in non-obstructive azoospermia patients." (PMID 35910569, 2022).
bacteremia (1 paper, 2024). "Further research is required to determine if Per2 or its gene Per2 could be used as reporters of bacteremia due to alcohol misuse." (PMID 38674014, 2024).